RNU6-1154P (RNA, U6 small nuclear 1154, pseudogene)
Gene: Small nuclear RNA gene on chromosome 7 (135,665,599 to 135,665,702, reverse strand). Ensembl gene ENSG00000212303.
Homologues: Orthologues: chimpanzee U6 (98% identical), macaque U6 (92% identical), dog U6 (75% identical). Paralogues in human: RNU6-1287P (87% identical), RNU6-204P (87% identical), RNU6-1175P (85% identical), RNU6-1209P (85% identical), RNU6-797P (85% identical), RNU6-843P (85% identical), RNU6-1131P (84% identical), RNU6-1152P (84% identical), RNU6-1273P (84% identical), RNU6-188P (84% identical), RNU6-398P (84% identical), RNU6-744P (84% identical), and 1289 more.